GSTP1 (glutathione S-transferase pi 1)
Diseases named in the same sentence as GSTP1 in open-access papers (continued):
Sharing a sentence is not in itself a finding about the gene and the disease.
prostate carcinoma (continued). "Similar molecular process of cancer development was shown in the case of SNP rs1695 (*Ile/Val + Val/Val) and SNP rs1138272 (*Ala/Val + Val/Val) in the GSTP1 gene that are associated with the lack of GST-π activity, and it can result in elevated the risk of prostate cancer development." (PMID 37819495, 2023). "A limitation of our current study is that we have not determined whether men with prostate cancer that are GSTP1 positive, whether they be from Black or White men, have had different exposures than men with prostate cancers that are GSTP1 negative." (PMID 34191807, 2021). "In addition, GSTP1 did not function as a tumor suppressor gene when using LNCaP prostate cancer cells in vitro and in vivo." (PMID 33628338, 2021). "Additionally, tetra-hydroxynonenal (4-HNE), a common byproduct of lipid peroxidation, was found to be reduced in GSTP1-positive prostate cancer patients compared to GSTP1-negative patients, indicating that GSTP1 protects lipids from oxidative damage." (PMID 33946704, 2021). "Similarly, we also found strong correlations of GSTM2 and GSTP1 promoter methylation with copy number alteration (CNA) burden in prostate cancer (Spearman’s ρ of 0.53 for GSTM2 and 0.49 for GSTP1), with both promoters among the promoters whose methylation is most strongly associated with CNA burden." (PMID 34871444, 2021). "Additionally, we have uncovered that putative epigenetic driver events, such as GSTP1 and GSTM2 hypermethylation in prostate cancer, may influence the acquisition of genetic driver events via their influence on the tumour mutation load." (PMID 34871444, 2021). "Hypermethylation of the CCND2 promoter is significantly higher in prostate cancers compared to normal prostate tissues (32%, 6% resp.; P = 0.004), and there are statistically significant concordances between methylation of CCND2 and the methylation of RARβ, GSTP1, CDH13, RASSF1A, and APC genes." (PMID 22191037, 2011). "Promoter methylation of GSTP1 is absent in normal epithelium and present in 6.4% of proliferative inflammatory atrophy, in 70% of high-grade prostatic intraepithelial neoplasia and in 90% of prostate cancer." (PMID 22191037, 2011). "Interestingly, the presence of GSTP1 protein itself does not influence prostate cancer cell proliferation, yet its DNA methylation and protein status seems to be indicative of the efficacy of DNMTi treatment." (PMID 21980513, 2011). "Absence of GSTP1 expression with promoter hypermethylation is evident in prostate cancer." (PMID 20671914, 2010). "GSTP1 methylation is evident in 90% of lymph nodes from prostate cancer patients but in only 11.1% of lymph nodes from noncancer patients, suggesting that detection of GSTP1 could have a role in molecular staging of prostate cancer." (PMID 20671914, 2010). "However, prostate cancers expressing GSTP1 have not been well characterized." (PMID 34191807, 2021). "Multiple genes, such as GSTP1, APC, MDR1, MGMT, and RASSF1A, show higher methylation frequency in prostate cancer samples compared to BPH and non-neoplastic prostate samples." (PMID 37234978, 2023). "A significant negative correlation between GSTP1 promoter methylation and IGF2-DMR0 methylation was found when considering all prostate cancer tissues (p = 0.00032, r = −0.308, Spearman’s rank correlation test)." (PMID 29017567, 2017). "Most notably, this has led to a commercially available test (ConfirmMDx for Prostate Cancer; MDx Health) with a reported negative predictive value of 90% in confirming negative biopsies based on qMSP analysis of APC, GSTP1, and RASSF139." (PMID 28084441, 2017). "This study involved patients with high index of suspicion of prostate cancer; APC and GSTP1 methylation ratios below the threshold (predicting no cancer) produced an NPV of 96% and 80%, respectively, indicating that APC has significantly higher NPV." (PMID 27351008, 2014).
prostate carcinoma (continued). "Moreover, the genes GSTP1 and SLCO2B1in 11q13 as well as the genes LHB and KLK3in 19q13were reported to involve in sex hormones metabolic pathway, though the previous study showed that the latter two genes were not so significant for risk factor in prostate cancer." (PMID 24146788, 2013). "Hazard ratios (HR) and 95% confidence intervals (CI) of prostate cancer mortality for methylation of APC and GSTP1 in the non-neoplastic tissue adjacent to the tumour (NTAT)." (PMID 23874531, 2013). "Hypermethylation of multiple genes (including GSTP1, RAR-2β, and APC) identified prostate cancer in histopathologically negative biopsy samples collected from men who were later positively diagnosed during a follow-up biopsy procedure." (PMID 20671914, 2010). "Finally, three pathway genes (GSTP1, GSTM5, RRM2) with non-zero coefficients were obtained for constructing the prostate cancer prediction model." (PMID 40426879, 2025).
breast carcinoma (153 papers, 1998 to 2025). "GSTP1 expressed in tumor-associated macrophages promotes resistance to the drug adriamycin in breast cancer treatment." (PMID 40290119, 2025). "The complete gene deletion of GSTM1 and the (GG) genotype of GSTP1 polymorphism (rs1695) have shown significant associations with breast cancer in South Indian74 and Jordanian women." (PMID 40290119, 2025). "In another study, Song and colleagues examined the combined diagnostic and prognostic value of HER2, Ki67, and GSTP1 in breast cancer, finding correlations with tumour size, lymph node metastasis, and TNM stage." (PMID 40951896, 2025). "The combination of the RARB + GSTP1 PMR was associated with breast cancer (OR = 2.81; 95% CI [1.02–8.22]; p = 0.026), controls under 50 years old (p = 0.048), patients older than 50 (p = 0.007), and postmenopausal (p = 0.034)." (PMID 37548362, 2023). "SNP rs1695 in the GSTP1 gene was also associated with an increased incidence of breast cancer (especially in Asian population) and development of CML." (PMID 37819495, 2023). "Based on a meta-analysis conducted in 2013 was found the correlation between the GSTP1 A/G gene polymorphism and the susceptibility to breast cancer in the Asian population." (PMID 37819495, 2023). "In conclusion, our study accounts for the first evidence of the association of promoter hypermethylation of RARB2 and GSTP1 genes in liquid biopsies (circulating cfDNA) and breast cancer in Peruvian women." (PMID 37548362, 2023). "It was discovered that the clinicopathological features of breast cancer were linked with GSTP1 methylation." (PMID 37901797, 2023). "Glutathione S-transferase P1 (GSTP1), which is associated with detoxification and glutathione conjugation, has been reported in adriamycin-resistant breast cancer cells." (PMID 37754253, 2023). "In another meta-analysis, it was also shown the association between the GSTM1 and GSTP1 gene polymorphisms and an increased risk of breast cancer occurrence in the Asian population (especially in East Asia)." (PMID 37819495, 2023). "Our study accounts for the first evidence of the association of promoter hypermethylation of RARB2 and GSTP1 genes in liquid biopsies (circulating cfDNA) and breast cancer in Peruvian women." (PMID 37548362, 2023). "Promoter hypermethylation of RARB + GSTP1 genes is associated with breast cancer, older age, and postmenopausal Peruvian patients." (PMID 37548362, 2023). "The promoter hypermethylation of RARβ2+GSTP1 is associated with breast cancer, older age, and postmenopausal patients." (PMID 37548362, 2023). "The findings of this study indicate that the GSTP1 c.313A > G mutation is an independent risk factor for neutropenia hematotoxicity in breast cancer patients induced by anthracycline-/paclitaxel-based chemotherapy." (PMID 35729577, 2022). "The goal of our study is to look into the link between GSTP1 gene polymorphisms and adverse reactions to anthracycline-/paclitaxel-based chemotherapy in breast cancer patients from the Meizhou Hakka ethnic group in southern China." (PMID 35729577, 2022). "This study retrospectively investigated pharmacogenetic associations of GSTP1 c.313A > G with chemotherapy-related adverse events in 142 breast cancer patients who received anthracycline and/or paclitaxel chemotherapy." (PMID 35729577, 2022). "In 57 breast cancer patients that underwent short partial breast irradiation (total dose 18–21Gy), a variant of the glutathione S-transferase pi 1 (GSTP1) gene was related to increased probability of grade 2 or above fibrosis or fat necrosis." (PMID 36230587, 2022). "In conclusion, the results of this study indicate that the GSTP1 c.313A > G mutation is an independent risk factor for neutropenia hematotoxicity induced by anthracycline-/paclitaxel-based chemotherapy in breast cancer patients." (PMID 35729577, 2022).
breast carcinoma (continued). "Although there have been several studies on the relationship between GSTP1 gene polymorphisms and chemotherapy toxicity in breast cancer, the findings are controversial, particularly in different populations." (PMID 35729577, 2022). "In a Danish trial including 150 women with breast cancer GSTP1 rs1138272 has been associated with docetaxel-induced peripheral neuropathy." (PMID 35501422, 2022). "Terrazzino did the research with 257 breast cancer patients who underwent surgery plus adjuvant radiotherapy and found GSTP1 Ile105Val was significantly associated with the risk of Grade 2–3 radiation-induced fibrosis, especially in skin fibrosis." (PMID 34238333, 2021). "Several studies investigated the role of GSTP1 rs1695 in breast cancer susceptibility or response to treatment." (PMID 33425072, 2020). "Pooled estimates of association of GSTP1 polymorphism and breast cancer risk, only studies with controls in Hardy-Weinberg equilibrium, high quality, matching, and genotyping examination done bindly or quality control." (PMID 32155154, 2020). "GSTM1 and GSTT1 null polymorphisms are associated with risk factors causing the Asian breast cancer and also GSTP1 Val105Ile (rs1695) polymorphism is a risk factor for Caucasians breast cancer." (PMID 33083304, 2020). "A total of fourteen previous meta-analyses between 2004 and 2016 have been published to analyze the individual GSTM1 present/null, GSTT1 present/null, and/or GSTP1 IIe105Val polymorphisms on breast cancer (BC) risk." (PMID 32155154, 2020). "Pooled estimates of association of the combined effects of GSTM1 present/null and GSTP1 IIe105Val and breast cancer risk, only studies with high quality, matching, HWE, and genotyping examination done bindly or quality control." (PMID 32155154, 2020). "Meta-analysis of the combined effects of GSTM1 present/null, GSTT1 present/null and GSTP1 present/null on breast cancer risk." (PMID 32155154, 2020). "Fourteen previous meta-analyses have been published to analyze the polymorphisms of individual GSTM1 present/null, GSTT1 present/null, and GSTP1 IIe105Val on breast cancer (BC) risk." (PMID 32155154, 2020). "Meta-analysis of the combined effects of GSTT1 present/null and GSTP1 IIe105Val on breast cancer risk." (PMID 32155154, 2020). "In this study, we evaluated the association of two common genetic variations (Ile105Val and Val114Ala) in the GSTP1 with breast cancer risk." (PMID 32334487, 2020). "Meta-analysis of the combined effects of GSTM1 present/null and GSTP1 IIe105Val on breast cancer risk." (PMID 32155154, 2020). "False-positive report probability values for the previous meta-analyses on GSTM1, GSTT1, and GSTP1 IIe105Val polymorphisms with breast cancer risk." (PMID 32155154, 2020). "GSTP1 increases breast cancer risk and aggressiveness but enhances response to cyclophosphamide chemotherapy in North China32." (PMID 31024008, 2019). "GSTP1, which is associated with detoxification and glutathione conjugation, has been reported in adriamycin-resistant breast cancer cells." (PMID 31324203, 2019). "Patients with breast cancer with the allele GSTP1 105Val are more likely to have a tumor with advanced histological grade, lymph node metastases, and negative estrogen receptor." (PMID 28761624, 2017). "Studies have investigated the associations of the GSTP1 (A313G) gene polymorphism with treatment response, prognosis, and toxicities for breast cancer." (PMID 29069838, 2017). "GSTP1 expression was closely associated with the response to chemotherapy and the clinical outcome of breast cancer." (PMID 29116019, 2017). "Clinicopathologic analysis revealed that GSTP1 expression was positively associated with CLDN6 in human breast cancer samples." (PMID 29116019, 2017). "This study aimed to investigate the association of the GSTP1 gene polymorphism with the outcomes and toxicities of treatments in breast cancer." (PMID 29069838, 2017).
breast carcinoma (continued). "For example, polymorphisms in the GSTM1 and GSTP1 genes increase the risk of developing breast cancer and hepatocellular carcinoma." (PMID 26682223, 2015). "Ethnicity-stratified analysis revealed that there were statistical associations between GSTP1 promoter methylation and increased breast cancer risk among both Caucasians (OR = 7.23, 95 % CI = 3.76–13.90) and Asians (OR = 11.71, 95 % CI = 5.69–24.07)." (PMID 26585467, 2015). "Previous study declared that the genetic variation of GSTP1 affected its enzymatic activity and detoxifcation ability, thereby contributing to breast cancer susceptibility." (PMID 26585467, 2015). "Further analyses on larger sample size are required to highlight the effect of GSTP1 G allele on breast cancer prognosis." (PMID 25648141, 2015). "We also performed subgroup analyses to further explore the potential effects of the patients’ ethnicity, sample type and detection method on the association of GSTP1 promoter methylation with the risk of breast cancer." (PMID 26585467, 2015). "Further analyses on larger sample size are needed to highlight the effect of GSTP1 G allele on breast cancer prognosis." (PMID 25648141, 2015). "In conclusion, our meta-analysis suggested a strong association between GSTP1 promoter methylation and breast cancer risk." (PMID 26585467, 2015). "After stratified by sample type, we found that aberrant methylation of GSTP1 was correlated with the risk of breast cancer detected in tissue (OR = 10.32, 95 % CI = 5.97–17.85) as well as blood samples (OR = 4.02, 95 % CI = 1.12–14.38)." (PMID 26585467, 2015). "The results showed that moderate heterogeneity existed in investigating the correlation of GSTP1 methylation and breast cancer risk detected in blood samples and quantitative method by subgroup analysis." (PMID 26585467, 2015). "Studies of the Finnish and Koreans showed that the GSTP1 105Val allele was associated with a lower risk of breast cancer." (PMID 23826324, 2013). "In this study, we observed that the GSTP1 105Val (Ile/Val and Val/Val) allele carriers had a higher risk of breast cancer than those with the homozygous Ile/Ile(OR = 1.38)." (PMID 23826324, 2013). "Our previous analyses suggest that methylation of GSTP1 in locally advanced breast cancer patients treated with doxorubicin was associated to survival." (PMID 24093668, 2013). "Result showed that the GSTP1 Ile105Val genotype was an independent factor associated with the DFS of breast cancer patients (RR = 0.77, 95% CI: 0.45-0.91; P < 0.001)." (PMID 23826324, 2013). "As a consequence, statistically significant increased risk was found between GSTP1 313A>G and breast cancer, esophageal cancer, bladder cancer, leukemia and other cancers." (PMID 23437223, 2013). "Since CTX was activated by hepatic cytochrome P450 enzymes and 4-hydroperoxycyclophosphamide (4-HC) is an active derivative of CTX in vivo, the 4-HC was used to treat the breast cancer cells with different genotype of GSTP1 105Val allele in vitro." (PMID 23826324, 2013). "In summary, our results demonstrated that among women in North China, the GSTP1 105Val allele carries a higher breast cancer risk and a risk of more aggressive tumors." (PMID 23826324, 2013). "The report in Shanghai revealed that breast cancer patients with the GSTP1 105Val allele had a 60% reduction in mortality risk after chemotherapy (HR = 0.4, 95% CI: 0.2-0.8)." (PMID 23826324, 2013). "ESR1 and GSTP1 were the only single genes associated with mitotically active and high-grade male breast cancers." (PMID 22765268, 2012). "In the present study, promoter hypermethylation was revealed to be the major factor underlying the loss of GSTP1 expression in breast carcinomas." (PMID 23226781, 2012). "A previous study revealed an association between GSTP1 methylation and tumor invasion, size, sentinel lymph node metastasis and progression in breast cancer." (PMID 23226781, 2012).